METTL3 (methyltransferase 3, N6-adenosine-methyltransferase complex catalytic subunit)
Diseases named in the same sentence as METTL3 in open-access papers (continued):
Sharing a sentence is not in itself a finding about the gene and the disease.
tumor (continued). "In hepatoblastoma, the abnormal expression of METTL3 can promote tumor progression, and the modification of m6A in tumor cells generally increases." (PMID 35022030, 2022). "In recent years, the potential of METTL3 as a tumor biomarker has been ascertained to correlate with the malignancy of cancer cells." (PMID 35255776, 2022). "METTL3 is also involved in elevating mTORC1 activity and glycolysis, thus contributing to tumor progression of HCC cell lines." (PMID 36008936, 2022). "As the major “writer”, METTL3 was frequently investigated in human cancers, either as an oncogene or a tumor suppressor." (PMID 35399719, 2022). "By analyzing clinical data of recruited HCC, higher METTL3 was detected in patients with lymphatic metastasis, ≥5 cm of tumor size, or stage III + IV." (PMID 35571490, 2022). "Xenograft tumor experiment in nude mice confirmed that METTL3 silencing repressed OS cell proliferation in vivo via the HDAC5/miR-142-5p/ARMC8 axis." (PMID 35396379, 2022). "METTL3 depletion in NK cells impairs NK homeostasis, renders NK cells hypo-responsive to IL-15 and hinders NK cell infiltration and function in the tumor microenvironment (TME)." (PMID 36085064, 2022). "Taken together, these findings strongly suggest that METTL3-mediated STEAP2 m6A modification plays a critical tumor-suppressive role in PTC progression." (PMID 35436987, 2022). "IHC staining of CD31, a marker of angiogenesis, also showed a significant decreased in tumor tissues of the METTL3 knockdown group compared with that in the control group." (PMID 35287752, 2022). "Potential correlations between METTL3 level and lymphatic metastasis, tumor size, tumor staging, and overall survival of HCC patients were analyzed." (PMID 35571490, 2022). "Paradoxically, we found that tumor suppressors were negatively correlated with the infiltration of pDCs, DCs, and cytotoxic cells, and the tumor promoters METTL3, VIRMA, and CBLL1 were positively correlated with Tcm and Th2 cell infiltration." (PMID 35223847, 2022). "Evidence accumulated in recent years suggests that METTL3 as an m6A methyltransferase plays a key role in cancer, both as an oncogene and as a tumor suppressor." (PMID 35742899, 2022). "METTL3 is an important regulator of malignant tumors, which can promote the malignant biological behavior of tumor cells." (PMID 35252180, 2022). "Methyltransferase-like 3 (METTL3) is a prominent RNA n6-adenosine methyltransferase (m6A) that plays an important role in tumor growth by controlling the work of RNA." (PMID 35742899, 2022). "NK-cell-specific deletion of METTL3 in mice disrupts NK cell infiltration and function in the tumor microenvironment, leading to tumor progression." (PMID 36008936, 2022). "On the other hand, METTL3 acts as a tumor suppressor in endometrial cancer and triple-negative breast cancer." (PMID 35436987, 2022). "The weight and growth curve of xenograft tumors showed that the METTL3 knockdown led to a significant reduction in the weight and volume of tumor tissues, while Ad-ACIN1 also reversed the sh-METTL3 roles." (PMID 35255776, 2022). "The results demonstrated the METTL3 inhibitor quercetin decreased the proliferation of two different tumor cell lines, which is consistent with the effect of METTL3 knockdown." (PMID 35571106, 2022). "In contrast, it was reported that METTL3 knockout in mouse GBM models inhibited tumor growth and development, and METTL3 knockdown in GSCs led to increased sensitivity of cells to radiation exposure." (PMID 36118889, 2022). "Depleting METTL3 in macrophages hindered macrophage activation, promoted anti-inflammatory and immunosuppressive activities and encouraged tumor growth and metastasis." (PMID 36085064, 2022). "Downregulation of METTL3 suppresses tumor growth and glycolysis progression in tumor cells and xenograft mouse models." (PMID 36071523, 2022).
tumor (continued). "Immunofluorescent staining (IF) and subcellular fractionation assay revealed predominantly cytosolic METTL3 in the non-invasive group, in contrast to its strong nuclear presence in invasive tumor cells." (PMID 36289222, 2022). "METTL3 is upregulated in GC tumor cells and is an independent prognostic factor of poor survival and an effective predictor for severity of GC." (PMID 36008936, 2022). "METTL3 is an important m6A methylation modification gene facilitating tumor progression by promoting tumor proliferation, migration, angiogenesis and other pathways." (PMID 36465351, 2022). "These phenomena suggested that METTL3 regulated the growth of xenograft tumour by regulating miR‐589‐5p." (PMID 35348293, 2022). "METTL3 is a known m6A writer that can facilitate tumor progression via an m6A-dependent mechanism in CRC." (PMID 36347844, 2022). "Studies of the same tumor conducted by different researchers revealed that the m6A-related proteins METTL3 and FTO were important, although different results were obtained." (PMID 35155557, 2022). "METTL3-mediated RNA N6-methyladenosine (m6A) is the most prevalent modification that participates in tumor initiation and progression via governing the expression of their target genes in cancers." (PMID 36465351, 2022). "By modulating the functions of oncogenes and tumor-suppressing genes via m6A modification, METTL3 plays essential roles in the development and progression of diverse cancers." (PMID 36614956, 2022). "Herein, according to the database analysis, we also found that METTL3 in PC cancer cells was correlated with a variety of tumor-infiltrating immune cells." (PMID 36058919, 2022). "Collectively, these results suggest that METTL3/CDC25B promotes HNSCC tumor growth and angiogenesis." (PMID 35287752, 2022). "METTL3 expressions were reported to be responsible indicator of tumor microenvironment and were used to predict the prognosis of pancreatic cancer patients." (PMID 35571490, 2022). "The results suggested that METTL3 expression was significantly higher in tumor tissues than in normal tissues in STAD, LIHC, and SRCC." (PMID 36614956, 2022). "In the present report, our cellular study in human ccRCC cell lines also demonstrated that when METTL3 was depleted, the cell viability, migration ability, invasion ability, and tumor formation in vivo, were significantly inhibited." (PMID 35794583, 2022). "Increasing lactate in tumor microenvironment induces METTL3 upregulation in TIMs via H3K18 lactylation." (PMID 36008936, 2022). "For instance, the metabolite lactic acid upregulates METTL3 expression in MDSCs by inducing histone lactonization, leading to increased m6A modification and immunosuppressive activity, and ultimately, tumor immune escape." (PMID 35794625, 2022). "Around 84% (27/32) of these paired samples contained tumor cells with significantly stronger nuclear METTL3 expression, indicative a sustained nuclear localization of METTL3 post metastatic dissemination." (PMID 36289222, 2022). "METTL3 serves a critical role in various cellular biological processes, such as promoting the anti-tumor immunity of natural killer cells." (PMID 35655464, 2022). "METTL3 expression was positively correlated with tumor size (P < 0.05) and tumor, node, metastasis (TNM) stage (P < 0.05)." (PMID 35094011, 2022). "Another up-dated study revealed that lactate derived from the tumor microenvironment drove the transcription of immunosuppressive genes in tumor-infiltrating myeloid cells via modulating Mettl3." (PMID 36092712, 2022). "We assessed the relationships between METTL3 expression levels and tumor immune infiltration levels, immune checkpoint gene expression, immune neoantigens, tumor mutation burden, microsatellite instability, and DNA mismatch repair gene expression." (PMID 36614956, 2022).
tumor (continued). "This target can act as a tumor suppressor or an oncogene, and the abnormal expression of METTL3 or METTL14 biases them toward the regulation of a certain target, thereby exhibiting the opposite effect." (PMID 36561529, 2022). "This translates clinically to a reduction in tumor size and weight, when METTL3 is knocked out stably in a murine model." (PMID 35563821, 2022). "After the xenograft tumour was collected after growing in mice for 30 days, we discovered that the tumour volume was inhibited by METTL3 silencing but promoted by miR‐589‐5p mimic as compared with the siNC+MC group (p < 0.001)." (PMID 35348293, 2022). "Subsequent in vitro and in vivo experiments have confirmed that downregulation of METTL3 inhibits tumor growth and metastasis." (PMID 35223847, 2022). "More importantly, we found that METTL3 regulated tumor progression by COL12A1-mediated MAPK signaling pathway." (PMID 35399719, 2022). "When Mettl3/14 was inhibited, the modification of mRNA in the tumor was reduced, leading to an increase in CD8+ T cells, and enhanced the response to anti-PD-1therapy by a series of signaling pathways." (PMID 35590394, 2022). "On the one hand, METTL3 was significantly downregulated in testicular germ cell tumor tissues, which positively correlated with the tumor-infiltrating levels of CD8+ T cells, CD4+ T cells, and NK cells." (PMID 36517820, 2022). "METTL3-mediated m6A modification has been shown to significantly improve the capacity of tumor-infiltrating myeloid cells to suppress the immune system and facilitate tumor immune evasion." (PMID 36386128, 2022). "METTL3 overexpression and KD show its role in GC cell proliferation, migration, and invasion in vitro and tumour growth in vivo." (PMID 35565411, 2022). "After the xenograft tumour was established in mice, the tumour volume was determined and the expressions of METTL3, miR‐589‐5p, MMP‐2, TIMP‐2, E‐cadherin, N‐cadherin and Vimentin in tumour tissue were detected by RT‐qPCR and Western blotting." (PMID 35348293, 2022). "To further explore the role of METTL3 in the tumor microenvironment, we conducted a correlation analysis between METTL3 expression level and tumor-infiltrating immune cell scores in PAAD patients from the TCGA database." (PMID 36058919, 2022). "Rescue experiments revealed that silencing STEAP2 partially rescued the tumor-suppressive phenotype induced by METTL3 overexpression." (PMID 35436987, 2022). "In that study, mice with conditional Mettl3 depletion in NK cells showed aggravated tumor progression and shortened survival, accompanied by suppressed infiltration and impaired tumor immunosurveillance functions of NK cells in the TME52." (PMID 35254013, 2022). "METTL3 is expressed at higher levels in tumor samples compared to normal liver cells and higher expression of METTL3 is correlated with worse survival outcomes in HCC patients." (PMID 36008936, 2022). "In the tumor immune microenvironment, METTL3 was negatively correlated with immune cells such as NK cells, B cells, T cells, DCs, and macrophages." (PMID 35813476, 2022). "METTL3 is elevated in tumor tissues and increases with progression of the tumor stage: a higher expression is associated with a worse prognosis." (PMID 35155557, 2022). "Downregulation of METTL3 leads to NK cell hyporesponsiveness to IL-15 and promotes tumor immune escape via targeted effects on protein tyrosine phosphatase-2." (PMID 35794625, 2022). "This enhances the activation of NF-kB and STAT3 through the ERK pathway in METTL3-depleted macrophages, leading to increased tumor growth and metastasis." (PMID 36085064, 2022). "Further detection of METTL3 expression showed that the expression of METTL3 in tumor tissues was significantly higher than that in adjacent tissues (p < 0.05)." (PMID 34980191, 2022). "It has also been demonstrated that down-regulation of METTL3 expression in human GC cells inhibits the proliferation and migration of tumor cells and inactivates the signaling pathway of Akt." (PMID 35711459, 2022).
tumor (continued). "Recent researches have shown that ALKBH5 and METTL3 can be regulated by epigenetic modification of their promoters in tumor progression." (PMID 35304463, 2022). "Among these m6A-related enzymes, METTL3 was originally identified as a methyltransferase and is involved in tumor progression." (PMID 36476503, 2022). "Here, the study proved that METTL3 promotes the proliferation of tumor cells by indirectly affecting MYC levels or directly methylating specific mRNAs to modulate ribosome levels and translation, resulting in tumorigenesis." (PMID 35053496, 2022). "We noticed that the cytosolic/nuclear ratio of METTL14 is always consistent with the ratio of METTL3 across tumor cell lines." (PMID 36289222, 2022). "Depending on its m6A methyltransferase activity, METTL3 plays an essential role in tumor progression." (PMID 36476503, 2022). "Consistently, our results demonstrated that METTL3 expression was correlated with tumor size, clinical stage, and distance metastasis, and the overall survival rate was worse in patients with higher METTL3 expression." (PMID 35396379, 2022). "Our results exhibited that METTL3 overexpression repressed tumor growth, elevated m6A level and circDLC1 expression, reduced miR-671-5p expression, and enhanced CTNNBIP1 expression." (PMID 35474040, 2022). "Subsequently, a related study unveiled a critical role of METTL3-mediated m6A methylation in the homeostasis and anti-tumor immunity of NK cells." (PMID 35254013, 2022). "uncovers a critical function for METTL3-mediated m6A modification in the hypoxic tumor microenvironment and identifies FOXO3 as an important target of m6A modification in the resistance of HCC to sorafenib therapy." (PMID 35440025, 2022). "The biological role and mechanism of METTL3 in HNSCC tumour growth, metastasis and angiogenesis were determined in vitro and in vivo." (PMID 35287752, 2022). "A positive correlation between protein expression levels of METTL3 and effector molecules in tumor infiltrating NK cells has also been found." (PMID 36008936, 2022). "Our results demonstrated that METTL3 silencing reduced tumor volume and weight (p < 0.01) and decreased the Ki67-positive rate (p < 0.01)." (PMID 35396379, 2022). "Meanwhile, METTL3 can upregulate PD-L1 expression and inhibition of METTL3 expression can enhance tumor immunity through PD-L1-mediated T-cell activation in vitro and in vivo." (PMID 35965524, 2022). "YTHDF1 cooperates with the METTL3 m6A effects to enhance the stability of c-Myc, therefore knockout METTL3 can inhibit the malignant progression of tumor cells." (PMID 35022030, 2022). "Current pharmacological studies have identified small molecular inhibitors for METTL3, showing promising results in inhibiting tumor progression and growth." (PMID 35886072, 2022). "In other words, application of METTL3 inhibitor is possible to produce anti-tumor effect and provide a solution for patients with refractory features." (PMID 33879256, 2021). "One study discovered that METTL3 was lower in RCC patients than in adjacent non-tumor tissues, thus serving as a tumor suppressor." (PMID 34381710, 2021). "Taken together, the data above suggested a vital role for METTL3 in macrophages in promoting tumour progression." (PMID 33654093, 2021). "To evaluate the potential of targeting METTL3 to activate antitumour responses, we tested anti-PD-1 therapy in B16 tumour metastasis models." (PMID 33654093, 2021). "Previous studies have shown that the catalytic core enzyme METTL3 plays critical roles in a variety types of cancer as an oncogene and a tumor suppressor." (PMID 34207099, 2021). "METTL3 is identified as an independent prognostic factor in CC due to its distinct correlation with tumor progression and poor survival of patients." (PMID 33879256, 2021).
tumor (continued). "m6A sequencing reveals that loss of METTL3 impairs the YTHDF1-mediated translation of SPRED2, which enhances the activation of NF-kB and STAT3 through the ERK pathway, leading to increased tumour growth and metastasis." (PMID 33654093, 2021). "Collectively, we first verify the function of m6A mediated by Mettl3 for BCa and expatiate on the network of Mettl3 in governing tumor angiogenesis in vivo." (PMID 33681207, 2021). "It has been reported that HBXIP is upregulated in cancers, which plays a role as a tumor promoter in cancer via driving metabolic reprogramming through METTL3-mediated m6A modification." (PMID 34332535, 2021). "Elevated expression of METTL3 enhanced tumor growth and metastasis by promoting maturation of miR-25-3 and activation of the PI3K/AKT pathway." (PMID 33879256, 2021). "Dataset analysis revealed higher expression level of METTL3 in HNSCC, which was associated with poor OS and advanced tumor grade." (PMID 33879256, 2021). "Recently, increasing studies have revealed the accumulation of m6A modification in human cancers, indicating the important role of METTL3 in tumorigenesis and tumor progression." (PMID 33879256, 2021). "METTL3, a part of N6‐adenosine‐methyltransferase, has been reported to play an important role in a variety of tumours." (PMID 33491264, 2021). "Mettl3- or Mettl14-deficient tumors increased cytotoxic tumor-infiltrating CD8+ T cells and elevated secretion of IFN-c, Cxcl9, and Cxcl10 in tumor microenvironment in vivo." (PMID 34804948, 2021). "Here, we discover that ablation of Mettl3 in myeloid cells promotes tumour growth and metastasis in vivo." (PMID 33654093, 2021). "Taken together, Mettl3-mediated m6A modification is required for the activation of TEK–VEGF-A-mediated tumor progression and angiogenesis." (PMID 33681207, 2021). "Based on the tumor-promoting effect of METTL3, the possibility of applying METTL3 inhibitors is further discussed, which is expected to provide novel insights into antitumor therapy." (PMID 33879256, 2021). "In other tumours, METTL3-methylated regulates the MALAT1-miR-1914-3p-YAP axis and increases YAP activity to enhance drug resistance and metastasis." (PMID 35004679, 2021). "For example, enrichment analysis uncovered the importance of METTL3 in glucose and lipid metabolism, but the specific mechanisms of METTL3 in tumor lipid metabolism were in infancy." (PMID 33879256, 2021). "Collectively, these data have testified that Mettl3 exerted its effect on tumor angiogenesis, supporting the role of Mettl3 as a collaborator of BCa progression by modulation of neovascularization." (PMID 33681207, 2021). "Surprisingly, METTL3 protein expression in NK cells from tumor-bearing mice was significantly decreased, and the suppressed METTL3 protein expression was increasingly evident with tumor progression." (PMID 34535671, 2021). "In contrast to increased m6A/METTL3 in most tumor types, decreased METTL14/m6A has been reported to act as a tumor suppressor, and elevated METTL14 expression has been reported in a variety of solid tumors and leukemia through various mechanisms." (PMID 33922187, 2021). "As one of the components of methyltransferase, METTL3 directly affects the methylation level of various tumor-related mRNAs, thereby contributing to the occurrence, development and prognosis of tumors." (PMID 34814861, 2021). "It was also found that excessive Mettl3 in cells of Upk3a origin contributed to promoting tumor growth by measuring tumor mass in mice." (PMID 33681207, 2021). "Hematoxylin and eosin stain (H&E) staining of xenograft tumors confirmed that METTL3 KD cell‐derived tumors exhibited significantly reduced tumor size and increased TMZ sensitivity." (PMID 34586728, 2021). "Here the authors show that m6A-methyltransferase METTL3 deletion in NK cells leads to reduced function and protection against tumour challenge through suppressing response to IL-15." (PMID 34535671, 2021).